IL17A (interleukin 17A)
Diseases named in the same sentence as IL17A in open-access papers (continued):
Sharing a sentence is not in itself a finding about the gene and the disease.
psoriasis (continued). "Psoriasis patients who were asymptomatic for SARS-COV-2 exhibited immune imbalance with high levels of IL-18, IL-17A and IL-6, and low levels of IL-27 compared to healthy controls." (PMID 34068473, 2021). "IL17A and TNFα, the key genes of the TNFα/IL23/Th17 axis in psoriasis, were significantly upregulated in psoriasis skin samples compared to healthy samples." (PMID 33807762, 2021). "Notably, the AUC values of all identified LPLs except lysophosphatidic acid (LPA) (20:4) were higher than 0.7 in both the PSO/CON comparison and the IXE/PSO comparison, which indicated that these identified LPLs may serve as predictive markers of the efficacy of IL-17A mAb treatment in psoriasis." (PMID 33602246, 2021). "In the active stage of psoriasis,the expression of IFN-γ, IL-17A and IL-22 in CD4+ and CD8+ T cells in the epidermis is increased." (PMID 34295334, 2021). "The infiltrated neutrophils produce IL-6, IL-17A, and TNF-α to stimulate keratinocytes, resulting in positive feedback to deteriorate psoriasis." (PMID 33754014, 2021). "IL-17A is mainly synthesized and secreted by TH17 cells and is considered to play a key role in the pathogenesis of psoriasis." (PMID 34044769, 2021). "In this study, a combination of IL-1α, IL-17A, IL-22, oncostatin M, and TNF-α (mix M5) was used to trigger psoriasis-like changes in NHEK cells in vitro." (PMID 34314383, 2021). "Down-regulation of IL-17A, IL-17F and IL-12B were detected as early as 2 weeks post-treatment with PF-06700841, suggesting the requirement of TYK2 and Janus kinase 1 for psoriasis signaling transduction." (PMID 34777377, 2021). "The present study showed that alantolactone decreased the mRNA levels of TNF-α, IL-6, IL-1β, IL-8, IL-17A, and IL-23, thereby suppressing Th1- and Th17-mediated cytokines and improving IMQ-induced psoriasis-like skin lesions and inflammation status in mice." (PMID 34202301, 2021). "Secukinumab (SEC) and ixekizumab (IXE) are monoclonal antibodies targeting IL-17A, and brodalumab (BRO) is a fully human monoclonal antibody targeting the IL-17 receptor A. All of them have demonstrated high efficacy for psoriasis in clinical settings." (PMID 33411857, 2021). "In this study, we found that PSORI-CM02 inhibited the proliferation and migration of IL-17A-stimulated HUVECs and reduced new blood vessel growth in the skin of mice with IMQ-induced psoriasis." (PMID 33995368, 2021). "The results are comparable to studies with gallic acid, a natural small molecule from radix of Paeoniae rubra, that also suppressed IL17A-mediated KRT16 and 17 expression in HaCaT cells and in an IMQ-psoriasis mouse model in vivo." (PMID 33801280, 2021). "Increased miR-146a has a strong positive correlation with IL-17A in psoriasis patients and can be induced by IL-1β, TNF-α, and IL-17A in human proliferating keratinocytes, indicating its potential roles downstream of IL-17A/TNF-α signals." (PMID 33718413, 2021). "Gene expression analysis in paw skin demonstrated increased expression of Tnf, Il1b, Il17a, and Il22 in mice injected with IL-23 EEV, consistent with the psoriasis-like changes seen on histology of the ears." (PMID 33983951, 2021). "These T cells induce psoriasis via the secretion of proinflammatory cytokines such as tumor necrosis factor-α (TNF-α), interleukin (IL)-17A, IL-23, and interferon-γ." (PMID 34445513, 2021). "Taken together, the ex vivo psoriasis skin model generated by tape stripping and stimulation with psoriasis cytokines (IL-17A, TNF-α and IL-22) turned out as a useful psoriasis ex vivo model, with psoriasin, BD2 and GLUT1 as psoriasis markers." (PMID 33801280, 2021). "We detected a variety of antioxidative/oxidative molecules in IL-17A-stimulated HUVECs and the skin lesions of mice with IMQ-induced psoriasis." (PMID 33995368, 2021). "In summary, treatment of HPK with the cytokines IL-17A, IL-22 and TNF-α results in a psoriasis-like phenotype." (PMID 33801280, 2021).
psoriasis (continued). "Plaque and guttate psoriasis patients showed significant CLA+ T cells-dependent CA-mediated induction of IL-17F, IL17A, and IL-9 compared to unstimulated CLA+T/EPI and CA-stimulated CLA−T/EPI cocultures." (PMID 33546306, 2021). "Epidermal keratinocytes respond to TNF-α, IL-17A, and IFN-γ, which are involved in the pathogenesis of psoriasis, in part by producing inflammatory cytokines, chemokines, and antimicrobial peptides." (PMID 34884474, 2021). "Meanwhile, the proliferation of keratinocyte was reduced when Th17 cells secreted less IL-17A and IFN-γ, which also played a role in improving psoriasis." (PMID 34044769, 2021). "Treatment of human keratinocytes with IL17A, TNF-α and IL-22 upregulates KRT17 by the transcription factor STAT3 that is constitutively phosphorylated in psoriasis." (PMID 33801280, 2021). "In our study, PSORI-CM02 suppressed the expression of angiogenic mediators, including VEGF, HIF-1α, VEGFR1, VEGFR2, and ANG1, in IL-17A-stimulated HUVECs and in mice with IMQ-induced psoriasis." (PMID 33995368, 2021). "In addition, Th17 responses are involved in IMQ-induced psoriasis-like lesions, and the combination of Acar and low-dose CsA could significantly modulate the serum and skin expression levels of Th17 cytokines (IL-17A, IL-22, and IL-23) compared with Acar alone or low-dose CsA alone." (PMID 32316255, 2020). "In psoriasis, keratinocytes recruit dendritic cells via CCL20, and the production of IL-23A by keratinocytes and dendritic cells recruits and activates IL-17A-producing Th17 cells, CD8+ T cells, innate lymphoid cells (ILC), and γδ T cells." (PMID 31964744, 2020). "The immunological pathways involving IL-23 and IL-17A (IL-23/TH17 axis), as well as TNF-α, have been demonstrated to play pivotal roles in the pathogenesis of psoriasis." (PMID 32382290, 2020). "HaCaT cells were stimulated with a cocktail of five proinflammatory cytokines (M5), including IL-1α, IL-17A, IL-22, oncostatin M, and TNF-α that has been demonstrated as an in vitro model of psoriasis." (PMID 33149756, 2020). "Upon stimulation of the skin of psoriasis patients, the CD8+CD103+CD49a- TRM cells in the epidermis seem to be reactivated and initiate IL-17A production." (PMID 33633737, 2020). "To test this, we analysed normal human epidermal keratinocytes (NHEKs), a major skin component, stimulated with the key mediators of psoriasis development, TNF-α and IL-17A." (PMID 32194991, 2020). "Clinical skin severity was assessed with the psoriasis area index (PASI), whilst ELISA detected the expression of TNF-α, IL-17A, and IL-22." (PMID 33253155, 2020). "In vitro, the expression of EZH2 and H3K27me3 was stimulated in human keratinocytes treated with mixture of psoriasis-related cytokines pool (TNF-α, IFN-γ, IL-17A, and IL-22)." (PMID 33011750, 2020). "As an example for back-translation utilities, we propose to monitor IL-17A and KLK-7 protein levels as preclinical surrogates to estimate the effectiveness of next-generation psoriasis therapy." (PMID 31953524, 2020). "Following the initial exploration, we selected prominent analytes to understand the relationships of IL-17A and KLK-7 in psoriasis and LRG-1 in ankylosing spondylitis subjects, respectively." (PMID 31953524, 2020). "The number of CD8+CD103+ TRM in the psoriatic epidermis correlates with epidermal thickness, and psoriatic skin-derived CD103+TRM produce IFN-γ, IL-17A, and IL-22, suggesting the important roles of TRM in the formation of psoriasis." (PMID 32823524, 2020). "In psoriasis, epidermal CD8+ TRM cells express CLA, CCR6, CD103 and IL-23R antigen and produce IL-17A during ex vivo stimulation." (PMID 31963581, 2020). "During psoriasis development, the increased expression of inflammatory cytokines, such as tumor necrosis factor (TNF)-α, interleukin (IL)-6, IL-17A, and IL-22 triggers uncontrolled inflammatory states and activates keratinocyte hyperproliferation." (PMID 32515468, 2020).
psoriasis (continued). "Therefore, taking into the literature reports and our research results into account, we may conclude that Notch-Hes1 signaling can regulate the two major sources of IL-17A, Th17 cells, and IL-17A+γδ+T cells, in psoriasis through different transcription factor pathway, respectively." (PMID 32454795, 2020). "We showed that the additive model of IL-17A and KLK-7 significantly captured more PASI score variability than univariate models in psoriasis." (PMID 31953524, 2020). "The expression of these molecules is upregulated in the lesional skin of psoriasis and is downregulated to normal levels by biologics targeting TNF-α or IL-17A." (PMID 32070069, 2020). "CXCL8 is regulated by other cytokines such as IL17A and IL1B, which is critical for the pathogenesis of psoriasis and influences lesional keratinocytes of psoriasis." (PMID 32785106, 2020). "Using approximately 150 plasma analytes tracked across three time points, we identified IL-17A and KLK-7 as biomarkers for disease severity and apremilast pharmacodynamic effect in psoriasis patients." (PMID 31953524, 2020). "qRT-PCR analysis revealed that unstimulated ear skin from PD-1−/− and WT mice contain similar low levels of psoriasis-related cytokines, IL-6, IL23-A, and IL-17A (P = 0.95, P = 0.57 and P = 0.21 by Mann–Whitney U test, respectively)." (PMID 33060784, 2020). "In this study, HPKs were treated with IFN-γ, IL-17A, IL-22 and TNF-α, to generate a psoriasis-like phenotype." (PMID 32316273, 2020). "IL-17A induces keratinocytes to express REG3A, and this process promotes the proliferation of keratinocytes after injury in psoriasis." (PMID 33132897, 2020). "Thus, IL-17A-producing CD8+CD103+ TRM cells may be associated with a progressive clinical course of psoriasis rather than the severity of skin lesions." (PMID 33633737, 2020). "Previous studies implicating TH17 cells in diseases, such as psoriasis, inflammatory bowel disease, RA, EAE, and MS, led us to examine the possibility that IL17A, IL17RA, and IL17RC regulate HSV-1 infectivity in vivo." (PMID 32516406, 2020). "By contrast, IL-17A and CCL20 genes were higher in psoriasis than in atherosclerosis tissue, whereas IL-17R was expressed at comparable levels." (PMID 32161545, 2020). "The HA-modified ethosomes showed specific adhesion CD44 in imiquimod-induced psoriasis-like inflamed skin, and that the increased topical drug delivery of curcumin reduced TNF-α, IL-17A, IL-17F, IL-22, and IL-1β mRNA levels; and lower CCR6 protein expression." (PMID 32848737, 2020). "On the other hand, inhibition of IL-36γ released by IL-17A-treated keratinocytes impaired either proliferation or ICAM-1 expression both in HDMECs and in an in vivo murine model of psoriasis." (PMID 32352958, 2020). "The expression of specific pro‐inflammatory cytokines/alarmins, such as IL‐17A, IL‐6, and lipocalin‐2 (LCN2), was higher in the serum of DKO* mice compared to DKO*K15 mice at day 30 after psoriasis‐like induction." (PMID 31556482, 2019). "IL-17A blockers are tested for chronic inflammatory diseases, such as Crohn disease (NCT00936585), spondyloarthritis (NCT03358134), and psoriasis (NCT03403036)." (PMID 31572188, 2019). "Gallic acid (GA), a natural small molecule from Radix Paeoniae Rubra with an anti-psoriatic effect, has been shown to suppress IL17A-mediated KRT16 and KRT17 expression by preventing activation of Nrf2 in vitro and in the IMQ-psoriasis mouse model in vivo." (PMID 31374826, 2019). "Here, we examined the preventative effects of different doses of MHP1-AcN on psoriatic skin lesions and IL-17A production and determined the optimum dose in a mouse model of IMQ-induced psoriasis." (PMID 31659208, 2019). "Because we have shown that TIPE2 suppresses IL-17A production by T cells during the development of IMQ-induced psoriasis, the percentage and absolute number of CD3+IL-17A+ T cells was significantly increased in the blood and ILN as expected." (PMID 31616442, 2019).
psoriasis (continued). "The rational for treatment with biological agents is given through significant overexpression of Il-17A, TNF-α, IL-1, IL-36 in GPP and in psoriasis." (PMID 31286990, 2019). "The mRNA levels of IL-21, IL-21R, IL-17A, IL-22, IL-23, RORγt, and IFN-γ were increased, whereas the mRNA level of Foxp3 was decreased in the PBMCs of psoriasis patients." (PMID 31440249, 2019). "Studies from Dr. Wang’s group has established an essential role of T cell-derived cytokines, including IFNγ, IL17A and IL22, in maintaining KRT6/16 and KRT17 expression in the chronic lesion of psoriasis." (PMID 31374826, 2019). "Our study revealed that, although TIPE2 exacerbates the development of psoriasis through promoting the directional migration of T cells to the site of inflammation, it alleviates EAU through the suppression of IL-17A production by T cells." (PMID 31616442, 2019). "Both IMQ-induced psoriasis and EAU model contains a strong T cell component and the disease development is dependent on IL-17A." (PMID 31616442, 2019). "In contrast, IL17A clusters together with IL23A and the other cytokines thought to be involved in psoriasis pathophysiology." (PMID 31019502, 2019). "Our results showed that IL-21R is highly expressed in PBMCs and in the lesional skin of psoriasis patients, and that IL-21 can promote CD4+ T cell proliferation and Th17 cell differentiation and also the secretion of IL-17A and IL-22." (PMID 31440249, 2019). "Because of its function in mediating IL-17A expression in TH17 cells as well as its role as a downstream mediator of IL-17A and IL-36 signaling in keratinocytes, it is speculated that induction of IκBζ in one of these cell types is responsible for the development of psoriasis." (PMID 31622280, 2019). "After silencing IL37, cells were stimulated with a mixture of five cytokines designated as M5 (IL-1α, IL-17A, IL-22, Oncostatin M, and TNF-α) to mimic the microenvironment of keratinocytes in psoriasis." (PMID 30918469, 2019). "The dominant role of the IL-23/IL-17A axis in psoriasis is also evident by the overwhelming clinical success of newly developed IL-23/IL-17A axis-targeting biologics, which could induce near complete resolution of psoriasis, even in the most severely affected individuals." (PMID 31019502, 2019). "Studies have reported an improvement of at least 75% as measured by the psoriasis area and severity index (PASI) in >80% of patients treated with anti-IL-17A therapy." (PMID 32010143, 2019). "Neutralization of IL-17A (secukinumab and ixekizumab) or the receptor subunit IL17RA (brodalumab) via monoclonal antibodies represents a highly effective approach to treat psoriasis." (PMID 30127781, 2018). "IL-17A and IL-17F production is probably the most relevant effect of S. pyogenes on CLA+ T cells in psoriasis." (PMID 30013558, 2018). "Like in the case of S. pyogenes, CLA+ T cells, together with autologous epidermal cells, preferentially respond to C. albicans extract by inducing IL-9, IL-17A, and IFN-γ production in psoriasis." (PMID 30013558, 2018). "Psoriasis is a common skin disease pathogenically driven by TNF and IL-17A-induced epidermal hyperproliferation and inflammatory responses." (PMID 30321197, 2018). "By contrast, IL-17A and CCL20 were higher in psoriasis than in atherosclerotic tissue, whereas IL17R gene was expressed at similar levels." (PMID 29971067, 2018). "These cultures were treated with a combination of 20 ng/ml IL-17A and 10 ng/ml TNF-α to model some of the inflammatory processes seen in psoriasis skin." (PMID 30321197, 2018). "Because MaR1 inhibits IL-17A production in IMQ-induced skin inflammation, it is necessary to confirm its effect using a more suitable psoriasis model, which is an intradermal IL-23-injected psoriasis model." (PMID 29615641, 2018). "The cytokines most convincingly demonstrated to mediate psoriasis plaque formation are those for which inhibition has been effective in patients, such as IL-23, TNF, and IL-17A." (PMID 29434599, 2018).
psoriasis (continued). "Decrease in the gene expression of IL-19, IL-17A, and IL-23 levels further confirms the potent effect of SEL001 on IMQ-induced psoriasis." (PMID 29867905, 2018). "IL-17A, mainly secreted by TH17 and γδT cells, played an important role in psoriasis through acting on keratinocytes to induce a series of changes in epidermis." (PMID 30341238, 2018). "Psoriasis lesions contain elevated levels of TNF-α and IL-17A, cytokines recognized as important mediators of cutaneous inflammation." (PMID 30321197, 2018). "Our present study shows that IL-23 acts directly on macrophages to induce IL-17A, IL-17F, IL-22 and IFN-γ productions which likely promote the severity of psoriasis-like dermatitis in mice." (PMID 29508278, 2018). "In psoriasis, TNF-α is thought to work synergistically with IL-17A by inducing IL-17 receptor (IL-17R) expression on keratinocytes, promoting the maturation of Th17 and Th22 cells, and increasing the production of IL-17A31." (PMID 30054515, 2018). "We developed an ex vivo organotypic skin culture model using full-thickness normal human skin stimulated with IL-17A and TNF-α to mimic disease-related molecular changes in psoriasis skin." (PMID 30321197, 2018). "Intracellular signals for many of the cytokines elevated in psoriasis lesions, including TNF and IL-17A, are transduced though the MAP kinase and NF-κB pathways." (PMID 30321197, 2018). "In an in vitro study using reconstituted human epidermal sheets, IL-17A stimulated greater transcriptional activation than IL-22 or IFN-γ, correlating with the psoriasis transcriptome." (PMID 30109481, 2018). "Based on our current understanding of the immunopathogenesis of psoriasis, biologics have emerged that target TNF, IL-12/IL-23p40 subunit, IL-23p19 subunit, IL-17A, and the IL-17 receptor α chain (IL-17RA)." (PMID 29642409, 2018). "To model the cytokine-induced keratinocyte responses seen in psoriasis, we treated human skin organ cultures with TNF-α and IL-17A." (PMID 30321197, 2018). "Cytokines play a central role in the psoriasis disease process, particularly IL-17A and TNF-α, as highlighted by the efficacy of recently-developed biologic drugs targeting these molecules in psoriasis." (PMID 30321197, 2018). "In fact, our study shows that IL-17A from CD8+ T cells, CD4+ T effectors, and CD4+ Tregs were also higher in psoriasis samples compared to controls." (PMID 30054515, 2018). "A. cinnamomea extract reduced psoriasis-like inflammation, infiltration of CD4+ T cells, CD8+ T cells, and neutrophils, and the expression of TNF-α, IL-17A, and IL-22 in imiquimod-induced psoriatic skin lesions." (PMID 28894754, 2017). "NHEK were stimulated by A-SAA or the cytokines IL-1α, IL-17A, IL-22, OSM, TNF-α alone or in combination, previously reported to reproduce features of psoriasis." (PMID 28708859, 2017). "We further stimulate cells both with A-SAA and IL-17A, we reported particularly involved in A-SAA synthesis by keratinocytes and in psoriasis pathogenesis." (PMID 28708859, 2017). "IL-17A and TNF-α play key roles in the complex inflammatory network of psoriasis, promoting immune activation, and the maintenance of psoriasis lesions." (PMID 28217129, 2017). "To determine the relevance of the effects of IL-17A in human skin diseases, we evaluated iNOS- and CD206-expressing cells in human psoriasis and AD samples." (PMID 28963556, 2017). "The data shown in our study revealed that inflammatory cytokines in plasma including IL-17A, IL-17 F, IL-22 and IL-23 were reduced with the attenuation of IMQ-induced psoriasis-like inflammation in the H and L group mice." (PMID 27581210, 2016). "Dermal γδ T cells are the main producers of IL-17A and IL-22 in IMQ-induced psoriasis-like skin disease." (PMID 26999594, 2016). "Taken together, various types of immune cells produce the psoriasis-driving cytokines TNF, IL-17A, and IL-22." (PMID 27158469, 2016).